CCL2 (C-C motif chemokine ligand 2)
Diseases named in the same sentence as CCL2 in open-access papers (continued):
Sharing a sentence is not in itself a finding about the gene and the disease.
lung carcinoma (continued). "Therefore, blocking the CCL2 signaling pathway may prove beneficial for halting lung cancer progression." (PMID 29207614, 2017). "Our results show that miRNAs-mediated FOXO3a/VEGF/CCL2 signaling plays a prominent role in LCCs-mediated NFs into CAFs, which may have clinical implications for providing novel biomarker(s) and potential therapeutic target(s) of lung cancer in the future." (PMID 27541266, 2016). "Co-introduction of functional CCR2 successfully enhanced in vivo anti-lung cancer reactivity mediated by infused double-transfected effector T cells, notably in the phase immediately after the start of therapeutic infusion, reflecting the increased tumor trafficking activity in response to CCL2." (PMID 23441216, 2013). "Co-culturing macrophages with lung cancer cell lines can upregulate CCR2/CCL2 and CX3CR1/CX3CL1 in both cancer cells and macrophages, playing a central role in lung cancer growth and metastasis." (PMID 40264773, 2025). "Parallel observations from Chinese lung cancer cohorts included enriched TNF-α pathway activity and higher plasma TNF levels, while elevated IL-10/CCL2 in elderly patients and ST6GAL1 in high-grade irAEs further highlight shared inflammatory axes." (PMID 40722787, 2025). "Lung cancer cells undergoing EMT secrete increased levels of chemokines and transcription factors, such as the chemokine CCL2 and the transcription factor ZEB1, further enhancing the recruitment and polarization of TAMs." (PMID 40304000, 2025). "Decreased expression of CCL2 in human SCLC and blockage of CCL2 in a mouse lung cancer model showed lower macrophage infiltration of tumors with a reduction in M2 polarization and, as a consequence, an increase in CD8+ T cell activation." (PMID 39114657, 2024). "RT-qPCR analyses of CCL2, CCL3, CCL13, and CCL17 revealed that the transcription level of CCL2 in lung cancer was notably elevated compared to that in healthy lung." (PMID 39135069, 2024). "The engagement of TLRs induced NF-κB activation via the TRAF6-TAK1 signaling axis and increases in the production of IL-6, CCL2, CCL20, vascular endothelial growth factor (VEGF), and MMP2, thereby enhancing lung cancer migration and invasion." (PMID 37287005, 2023). "Conditioned media from both lung cancer cell lines increased (p < 0.0001) VEGF and CCL2 mRNA expression by 6- and 8-fold, respectively, indicating successful polarization to a tumor-educated phenotype." (PMID 36670978, 2023). "The engagement of TLR3/4 was reported to induce increases in the production of IL-6, CCL2, CCL20, VEGF, and MMP2 through NF-κB activation, thereby enhancing lung cancer migration and invasion." (PMID 37287005, 2023). "Thus, GPX8‐mediated secretion of IL6 and CCL2 by CAF in TME may promote lung cancer metastasis." (PMID 35978854, 2022). "Previous reports have demonstrated that TLR3/4 activation can increase the production of IL-6, CCL2, MMP2, and CCL20 cytokines by promoting TRAF6 ubiquitination and autophagy induction, thereby facilitating the migration and invasion of lung cancer cells." (PMID 35422093, 2022). "Autophagy induced by TLR4 or TLR3 activation can enhance the production of cytokines such as IL-6, CCL2, MMP2, and CCL20 by promoting TRAF6 ubiquitination, thus facilitating the migration and invasion of lung cancer cells." (PMID 35422093, 2022). "Again, many of the immune-modulatory genes differentially expressed in the mouse model were site-specifically recapitulated, e.g., higher CCL2, CXCL5, CXCL9, CXCL11, CXCL14, CXCL17, and IDO1 in lung cancers and higher CXCL12, FGL1, and LAG3 in liver cancers." (PMID 33985562, 2021). "Both cytokines (IL-6, 10, 17, 27, 35; TNF-α; IFN-γ; TGF-β) and chemokines (CCL-2, 5, 18; CCR-4; CXCR-4; CX3CL-1; CXCL-1, 5, 8, 13) are very commonly targeted for lung cancer treatment, considering their biomarker roles." (PMID 34336101, 2021).
lung carcinoma (continued). "CCL2 (or monocyte chemotactic protein 1 (MCP1)) displays overexpression in TAM and triggers EMT in lung cancer with IL-6 through activation of Twist/STAT3." (PMID 34220337, 2021). "One study stressed the involvement of CCL-2/CCR-2 signalling in tumour progression and metastasis in lung cancer patients." (PMID 34336101, 2021). "The chemokine CCL2 recruits myeloid cells to the TME in vivo and is primarily secreted by lung cancer cells and myeloid cells in the TME." (PMID 32528880, 2020). "Expression of CCL2, CCR2 or in combination with IL6 and IL10 correlates with a worse prognosis in lung cancer patients." (PMID 32219066, 2020). "In the present study, we proved that ERα expression in lung cancer cells can promote NSCLC invasion through increase of and cross‐talk with infiltrated macrophages via up‐regulating the CCL2‐ and CXCL12‐involved signal pathways." (PMID 32356397, 2020). "TLR4-induced autophagy activation promoted migration and invasion of lung cancer by induction of chemokines and immunosuppressive factors, such as IL-6, MMP2, and CCL2." (PMID 33172060, 2020). "We found known lung cancer drivers such as Lipoprotein Lipase (LPL) and CC Chemokine Receptor 2 (CCL2)." (PMID 31640282, 2019). "Recently, a report from Zhang and group have suggested that treatment with BAP promotes the migration and invasion of lung cancer cells through up-regulating the expression of cytokine IL8 and chemokines C-C motif Ligand 2 (CCL2) and CCL3." (PMID 31252679, 2019). "For instance, the SAA1 lung cancer biomarker, neuro-inflammation factor MMP1, the chemokine ligands (C-C motifs) CCL2, CCL5, and CCL20, and cytokines such as IL6, IL8, IL16, were all significantly modulated." (PMID 26950733, 2016). "Combined our PPI network analysis with previous studies, PRAME knockdwon upregulates MMP1, CCL2, CTGF, and PLAU and contribute to lung cancer metastasis." (PMID 27391090, 2016). "Knockdown of PRAME decreases the expression of E-Cadherin and promotes the proliferation, invasion, and metastasis of lung cancer cells by regulating multiple critical genes, most of which are related to cell migration, including MMP1, CCL2, CTGF, and PLAU." (PMID 27391090, 2016). "It has recently been shown that NF-κB enhances the expression of T cell chemokines CCL2 and CCL5 to increase T cell tumor infiltration and tumor rejection in mouse tumor models and human lung cancer patients." (PMID 27014915, 2016). "A HLA-A2402+ human lung cancer cell line, LK79, which expresses high amounts of both CCL2 and WT1 mRNA, was employed as a target." (PMID 23441216, 2013). "Various amounts of CCL2 protein were produced in all of the lung cancer cell lines assessed, among which LK79, a SCLC cell line, produced notably high amounts of CCL2." (PMID 23441216, 2013). "Human lung cancer cells variously express a tumor antigen, Wilms' Tumor gene product 1 (WT1), and an inflammatory chemokine, CCL2." (PMID 23441216, 2013). "TLR3/4 activation results in the upregulation of chemokines CCL2/MCP-1 and immunosuppressive factors VEGFA and MMP2, which collectively promotes lung cancer invasion and metastasis through the adaptor protein TICAM1/TRIF and the activation of downstream MAPK/NF-κB signaling pathway." (PMID 41293166, 2025). "Blocking CCL2 activates CD8+ CTLs, leading to reduced tumorigenesis of lung cancer." (PMID 39749673, 2025). "Thus, we tried to solve an important unanswered question: How chronic hypoxia affects the regulation of CCL2 expression in LUAD and its involvement in lung cancer progression." (PMID 35658112, 2024). "We believe that CCL2 could be a probable target for the diagnosis and therapeutics of NSCLC, and this study may expand our understanding of lung cancer." (PMID 37850256, 2024).
lung carcinoma (continued). "For example, tumor-cell-secreted factors like CCL2 and CSF1, contribute to the recruitment and survival of TAMs, which in turn promote immune evasion, cancer proliferation, epithelial-mesenchymal transition, and tumor invasiveness in lung cancer." (PMID 37656220, 2023). "In early-stage lung cancer nodules and metastatic lung cancer, IGFBP7+PLVAP+ tumor ECs were greatly amplified, whereas the proportion of extra-alveolar capillary ECs (cECs), EDN1+CCL2+ ECs, decreased." (PMID 37187731, 2023). "We found that propionate inhibited TLR2- and TLR3-induced lung cancer migration, invasion, and colony formation accompanied by the inhibition of the cAMP-AMPK-TAK1 signaling axis for the activation of NF-κB and the production of CCL2, IL-6, and MMP2 cytokines." (PMID 37287005, 2023). "Moreover, during the progression of lung cancer, the proportion of EDN1+CCL2+cECs decreases, while the proportion of IGFBP7+PLVAP+ECs significantly increases." (PMID 37187731, 2023). "The expression level of GPX8 was positively correlated with CCL2 and IL6 in lung cancer." (PMID 35978854, 2022). "DT treatment resulted in decreased expression of CCL2 and C-X-C motif chemokine ligand 1 (CXCL1) and increased expression of IL-8, blocking the ability of macrophages to promote lung cancer cell migration and the recruitment of macrophages by lung cancer cells." (PMID 36212483, 2022). "It has been shown that anti-CCL2 antibodies blocking the effects of CCL2 such as reducing MDSC, increasing CD4+ and CD8+ T cell infiltration, and promoting IFNy secretion can enhance the tumor immune effect of PD-1 in treating lung cancer in mice." (PMID 34603645, 2021). "Interestingly, the estrogen receptor α promotes cancer cell invasion via the increase of and cross-talk with infiltrated macrophages through the CCL2/CCR2/MMP9 and CXCL12/CXCR4 signaling pathways at least in lung cancer." (PMID 34833360, 2021). "Comparing 142 lung cancer patients with 141 non-lung cancer subjects, CCL2 was significantly elevated in lung cancer patients." (PMID 33297571, 2020). "Indeed, our results show that blocking the ERα/CCL2 axis by shCCL2 can reduce macrophage M2 polarization and MMP9 production, which will further lead to the change of invasion of lung cancer cells." (PMID 32356397, 2020). "To validate the critical role of CCL2 in controlling the migration ability of DT-treated lung cancer cells, we investigated the effects of DT with or without CCL2 on the migration ability of macrophages." (PMID 29207614, 2017). "However, to determine whether the HIF‐1A‐induced downregulation of CCL2 expression is mediated through miR‐210‐3p, we analyzed mir‐210‐3p expression in HIF‐1A silenced and overexpressed A549 lung cancer cells." (PMID 35658112, 2024). "Interestingly, lung cancer patients after induction of chemotherapy showed no significant change expect for increases in the level of CCL-2." (PMID 37580655, 2023). "Interestingly, increases in VEGF and CCL2 mRNA were either dampened or absent in Nrf2 KO BMDMs cultured in conditioned media from murine lung cancer cells." (PMID 36670978, 2023). "Our present work shows MLN4924-treated lung cancer cells had lower gene expression of CCL2 and CSF1 (data not shown) than controls, suggesting that CCL2, CSF1 may participate in modulating the TAM infiltration in LUAD." (PMID 37656220, 2023). "Moreover, stimulation with TLR4 and TLR3 can induce the production of IL-6, CCL2/MCP-1, CCL20/MIP-3α, VEGFA (vascular endothelial growth factor A), and MMP2 known to play pivotal roles in the migration and invasion of lung cancer cells through induction of autophagy." (PMID 37443143, 2023). "Importantly, we found that FFAR2KO A549 and FFAR2KO H1299 lung cancer cells exhibited the enhancement of cell migration, invasion, and colony formation induced by TLR2 and TLR3, along with increases in the production of CCL2, IL-6, and MMP2 cytokines." (PMID 37287005, 2023).
lung carcinoma (continued). "Our results showed that CCL2 mRNA expression and CCL2 secretion could not be activated in MRE11-knockdown lung cancer cells after macrophage activation." (PMID 36547079, 2022). "It has been previously reported that certain genes may be critical in the pathogenesis of systemic sclerosis (chemokine CCL2 and CXCL4) and lung cancer (including EGFR and HER2), but our results are more convincing in terms of reliability and universality owing to the large sample size." (PMID 33691643, 2021). "Therefore, in this review, we summarized the published literature from the year 2000 to the year 2019, specifically focusing on the role of IL6, TNFα, IL10, CCL2, CX3CL1, IL8 in the macrophages-tumor cells crosstalk; leading to lung cancer development and progression." (PMID 32219066, 2020). "Furthermore, tanshinone IIA exerts cardioprotective effects by reducing CCL2 and TGF-β1 secretion from cardiac fibroblasts; however, the effects of DT on cytokines secretion from lung cancer cells and macrophages remain unclear." (PMID 29207614, 2017). "Notably, FFAR2KO human lung cancer FFAR2KO A549 and FFAR2KO H1299 cells showed marked increases in cell migration, invasion, and colony formation in response to TLR2 or TLR3 stimulation, accompanied by elevations in NF-κB activation, cAMP levels, and the production of CCL2, IL-6, and MMP2 cytokines." (PMID 37287005, 2023). "After the knockdown of MRE11 in lung cancer cells, we discovered that IL-6 or the conditional medium of THP-1 cells can induce the mRNA expression of STAT3 downstream genes, including CCL2, in the control cells, but not in MRE11-knockdown lung cancer cells." (PMID 36547079, 2022). "Based on the cytokine array of supernatants derived from coculture, CCL2 and CXCL1 were elevated in three lung cancer cell lines (HCC4006, A549, and H1975) irrespective of coculture." (PMID 36612121, 2022).
pulmonary fibrosis (157 papers, 2004 to 2026). Chronic progressive interstitial lung disorder characterized by the replacement of the lung tissue by connective tissue, leading to progressive dyspnea, respiratory failure, or right heart failure. "IL-13 and CCL2 secreted by Th2 were implicated in the pathogenesis of lung fibrosis models, including in idiopathic pulmonary fibrosis." (PMID 36148463, 2022). "Among genes found to be associated with pulmonary fibrosis processes, only CCL2 and CXCL8 have already been associated with CIPF." (PMID 33384697, 2020). "CCL2 protein has been implicated in lung inflammatory disorders and contributes to the development of pulmonary fibrosis." (PMID 33233425, 2020). "Further studies have also implicated CCL2 with roles in multiple inflammatory diseases such as Alzheimer's Disease, Multiple Sclerosis and pulmonary fibrosis." (PMID 26358505, 2015). "Afterward, we used Metascape for the pathway enrichment analysis of this network, and we found that the most significant terms within the cluster consisting of EGF, IL-1β, IL-3, TNF-α, CCL2 were associated with lung fibrosis and proinflammatory/fibrotic mediators." (PMID 36733673, 2023). "These experiments have established that miR-199a-5p is directly or indirectly involved in the regulation of genes previously associated with lung fibrosis: CCL2, a potent mononuclear cell chemoattractant, PLAU, a component of the fibrinolysis system, TGFBRI, the TGFβ receptor type I, MMP3 and CAV2." (PMID 23459460, 2013). "Although several chemokines influence monocyte trafficking, CCL2 appears to be critical, as mice deficient in CCL2 have decreased recruitment of monocytes in response to infection and chemotactic stimuli and are protected from models of human disease like pulmonary fibrosis." (PMID 17888174, 2007). "CCR2 deficient mice, like CCL2 deficient mice, are unable to recruit monocytes to sites of inflammation, fail to clear certain intracellular pathogens and are protected from lung fibrosis." (PMID 17888174, 2007). "Moreover, mice with IL-10-induced pulmonary fibrosis showed significantly increased numbers of M2 macrophages in both bronchoalveolar lavage and lung tissue than normal mice, which was associated with enhanced expression of C-C motif chemokine ligand 2 (CCL2)." (PMID 32708044, 2020). "Studies have shown that RRAS can inhibit the secretion of inflammatory mediators such as TNFα and CCL2 by endothelial cells, reduce fibroblast activation, and alleviate pulmonary fibrosis." (PMID 40002743, 2025). "Knockdown of CCL2 expression alleviated pulmonary fibrosis and reduced the expression of COL1A1 protein and α-SMA protein." (PMID 40606673, 2025). "In mouse models of bleomycin-induced pulmonary fibrosis, transcriptional analysis has shown a significant increase in CCL2 expression." (PMID 39850880, 2024). "Gamma-herpesvirus infection up-regulates Ccl2 production and exacerbates pulmonary fibrosis in mice, with increased fibrocyte recruitment into the lungs in wild-type but abrogated in Ccr2-/- mice." (PMID 39768150, 2024). "Pirfenidone attenuates fibrocyte mobilization in bleomycin-induced pulmonary fibrosis in mice by reducing Ccl2 production in vivo and fibrocyte migration in vitro." (PMID 39768150, 2024). "This inhibition reduces CCL2 production, highlighting CCL2 as a key molecule in pulmonary fibrosis development." (PMID 39850880, 2024). "NFATc3+/+ mice subjected to BLM-induced pulmonary fibrosis showed increased accumulation of fibroblast foci, extracellular matrix protein deposition, fibrotic markers and CCL2 and CXCL2 production." (PMID 37523510, 2023). "The role of CCL2 in the pathogenesis of pulmonary fibrosis has long been recognized, where elevated levels of CCL2 was observed in the lungs of both IPF patients and animal models." (PMID 37523510, 2023). "Overall, our results indicate that CCL2 plays critical roles in the regulation of macrophage polarization and the development of pulmonary fibrosis." (PMID 37667317, 2023).